HSF1 (heat shock transcription factor 1)
Diseases named in the same sentence as HSF1 in open-access papers (continued):
Sharing a sentence is not in itself a finding about the gene and the disease.
cancer (continued). "Targeting DYRK2 has proven to be a tractable strategy to target cancers sensitive to proteotoxic stress; however, the development of HSF1 inhibitors remains in its infancy." (PMID 36622366, 2023). "Understanding the processes through which cancer cells gain resistance to HSF1 inhibition is also an important line of research." (PMID 37958341, 2023). "Since HSF1 is a central regulator of stress responses, various studies have demonstrated its implication in cancer development, showing it to be an important target in cancer therapy." (PMID 36765939, 2023). "Many tumors exhibit altered ECM stiffness, therefore it is possible that this mechanism contributes to the activation of HSF1 in many cancers." (PMID 38164224, 2023). "Inhibiting ABL2 blocks the activity of HSF1 and its targets, which are essential for cancer cell growth and survival." (PMID 37958341, 2023). "In the last decade, important roles for HSF1 in cellular transformation and cancer development have been extensively studied." (PMID 37153737, 2023). "Activated HSF1 boosts the production of HSPs, shielding cancer cells from the harmful impact of chemotherapy drugs." (PMID 37958341, 2023). "HSF1 is one of the pan-cancer targets because of its upregulation and significance for the maintenance of numerous oncogenic pathways." (PMID 37153737, 2023). "HSF1 inhibition has been shown in studies to effectively diminish critical cancer features such as cell proliferation, survival, and metastasis." (PMID 37958341, 2023). "Targeting HSF1 for cancer therapy is still in the pre-clinical stage but it has been suggested to be a promising modality in cancer treatment." (PMID 37153737, 2023). "HSF1 is overexpressed in cancer cells and participates in the migration, invasion, and proliferation of malignant tumors." (PMID 36830941, 2023). "Recently, heat shock factor 1 (HSF1) is recognized as an important component of tumor immunotherapeutic response as well as related to PD-L1 expression in cancer." (PMID 36482717, 2023). "With its important roles in tumorigenesis and tumor progression, targeting HSF1 offers a novel cancer treatment strategy." (PMID 37958341, 2023). "HSF1, a protein involved in cellular stress responses, is frequently overexpressed in cancer cells, contributing to tumor growth and resistance to treatment." (PMID 37958341, 2023). "In this work, we show that nanoparticle-mediated TRPV1 blockade selectively suppresses stressful HSP70 and TGFβ1 via effective modulation of heat shock factor 1 (HSF1) for augmented thermo-immunotherapy against highly malignant tumors." (PMID 37120615, 2023). "Here, we performed firstly a bioinformatics analysis on HSF1 expression feature in HCC by exploring the public cancer databases including GEPIA, UALCAN and Oncomine databases." (PMID 36482717, 2023). "In this article, we review the essential roles and mechanisms of HSF1 action in cancer cells, focusing more on recently discovered functions and their underlying mechanisms to reflect the new advances in cancer biology." (PMID 37153737, 2023). "A large amount of evidence supports an important role for HSF1 in cancer development, during which HSF1 modulates multiple pathways including cell proliferation, cell survival, protein synthesis and energy metabolism." (PMID 37153737, 2023). "For example, fucosyltransferase IV (FUT4) promotes cell proliferation via both MAPK and PI3K-AKT pathways and was found to be upregulated by HSF1 to promote cancer cell proliferation." (PMID 37153737, 2023). "HSF1 inhibition has been demonstrated to sensitize cancer cells to chemotherapy, diminish tumor growth, and improve radiation therapy efficacy." (PMID 37958341, 2023).
cancer (continued). "HSF1’s regulatory mechanisms can be changed in cancer cells, resulting in different patterns of activation and function." (PMID 37958341, 2023). "The function of HSF1 in cellular transformation and cancer development has been extensively studied in recent years." (PMID 37153737, 2023). "Many experimental data indicate that HSF1 is indispensable for cancer cell migration and invasion, which plays an important role in cancer progression." (PMID 37894333, 2023). "Since then, HSF1 inhibitor NXP800 has entered Phase I trials for patients with advance cancers (NCT05226507)." (PMID 36622366, 2023). "The mechanisms of HSF1-induced tumorigenesis are complex and involve diverse signaling pathways, dependent on cancer type." (PMID 37958341, 2023). "Overexpression of HSF1 enhances the development of polyploidy, a common feature in cancer cells, and it can improve tumor progression, inferior outcome, progressive stage, and therapy resistance." (PMID 37958341, 2023). "Inhibition of HSF1 has been shown to sensitize cancer cells to chemotherapy and reduce tumor growth." (PMID 37958341, 2023). "The Alfred Tissières Young Investigator Award was awarded to Ruth Scherz-Shouval (Weizmann Institute of Science, Israel) for her outstanding work on roles of HSF1 in cancer." (PMID 36602710, 2023). "HSF1, shown to promote cell growth in human cancer was found down-regulated in cHL after N3a-treatment." (PMID 37568720, 2023). "HSF1 is often overexpressed in various cancer cells, fueling malignancy and indicating a poor prognosis." (PMID 37958341, 2023). "Another study reports an association between HSF1 and F-box and WD repeat domain-containing protein 7 (FBXW7), an important tumor suppressor for human cancer." (PMID 37958341, 2023). "HSF1 regulates several cell death pathways, including apoptosis, autophagy, endoplasmic reticulum (ER) stress and ferroptosis, all critical for cancer cell survival." (PMID 37153737, 2023). "Modulating the proteostasis network in cancer cells by inhibiting actors of the HSF-1 pathway, such as HSP90 or the HSF-1 protein itself, is an intensely studied approach in cancer treatment." (PMID 36980299, 2023). "Hyperactivation of HSF1 in cancers likely stems from the presence of several cellular stressors in cancer cells and the tumour microenvironment." (PMID 35080342, 2022). "The more likely explanation for the association between HSF1 activity and mTORC1 activity in these cancer datasets is that HSF1 has been shown to enhance mTORC1 activity via suppression of JNK." (PMID 35080342, 2022). "This is in line with a recent finding demonstrating that HSF2 occupies the same target genes with HSF1 in cancer to drive malignancy." (PMID 35687139, 2022). "It is widely known that HSF2 interacts with HSF1, surprisingly, they performed The Cancer Genome Atlas (TCGA) gene expression analysis in 21 cancers and examined which HSF has highest expression." (PMID 36430241, 2022). "We then analyze the functions of HSF1 in cancer biology, links between its expression patterns and key oncogenic pathways, and clinical significance in specific types of cancer." (PMID 35311075, 2022). "SIRT1 is upregulated in many cancers, potentially contributing to a chronic hyperactivation of HSF1 in malignancy." (PMID 35311075, 2022). "Both Clu and Hsp90aa were significantly enriched in the HSF1-bound fraction compared to IgG control, demonstrating direct regulation of these genes by HSF1 in cancer-conditioned PSCs." (PMID 36316305, 2022). "Another point is the importance of HSF1, it has a vital role in protecting cancer cells from apoptosis and helping them to invade from the immune system by metastasis." (PMID 35990198, 2022).
cancer (continued). "In line with our in silico analysis study, high levels of HSF1 have been identified in different types of cancers." (PMID 35938032, 2022). "More importantly, DTHIB significantly suppressed the HSF1 cancer gene signature and greatly inhibited tumor growth in mice." (PMID 35180892, 2022). "A robust upregulation of HSF1 mRNA in DLBC lymphoma can at least partially be responsible for strong increases in gene expression for most HSPs in this cancer." (PMID 35311075, 2022). "HSF1 was remarkably correlated with the levels of infiltrating cells and immune checkpoint genes in various cancers." (PMID 36069792, 2022). "The development of more specific inhibitors with better pharmacokinetic properties is needed for targeting of HSR components, including HSF1, for successful cancer therapy." (PMID 35311075, 2022). "As HSF1 is highly correlated with heat shock response and tumor pathogenesis, the KRIBB11 is usually used to investigate the correlation between HSF1 and cancers: the inhibition of HSF1 activity by KRIBB11 treatment can suppress the growth of tumor cells." (PMID 35370703, 2022). "Although HSF1 has been found to be a significant factor in the development and low prognosis of various chemotherapy cancer treatments, there are still very few effective inhibitors of HSF1." (PMID 35268755, 2022). "Research into PI3K, HSF1, and Pin1 have also suggested that the inverse relationship between AD and cancer stems from a dysregulation in both diseases, but in opposite directions." (PMID 36554301, 2022). "The transcription factor heat shock factor 1 (HSF1) is a master regulator of the proteotoxic stress response, supporting tumorigenesis by helping cancer cells cope with proteotoxic stress." (PMID 36104345, 2022). "A recent study identified Direct Targeted HSF1 InhiBitor (DTHIB), a new HSF1 inhibitor that directly binds to the DNA binding domain of HSF1 and selectively promotes its degradation in the nucleus of cancer cells." (PMID 35180892, 2022). "In fact, Cinnamon and its active components kill cancer cells directly by their regulating act on transcription factors such as HSF1, and kill indirectly by increasing of ROS production and mitochondrial dysfunction." (PMID 35990198, 2022). "The kinases known to activate HSF1 and tested in this current study all have been shown to be dysregulated in several cancers." (PMID 35080342, 2022). "In this paper, we already described (see Section 5.3), they finally suggested that HSF2 as a critical cofactor of HSF1 in driving a cancer cell transcriptional program to support the anabolic malignant state." (PMID 36430241, 2022). "HSF1 has a carcinogenic role in regulating proliferation, survival, invasion and metastasis of cancer cells." (PMID 35006040, 2022). "HSF1 is known to be overactive or overexpressed in many cancer types including prostate cancer, pancreatic cancers, breast cancer, colorectal, lymphomas, melanoma, oral cancers, and so forth." (PMID 35268755, 2022). "In contrast to neurodegenerative diseases, where an over-activation of HSF1 is a promising approach to protect affected cells from further damage, cancer cells can use the protective function of the active HSF1 for promoting a malignant state." (PMID 35218516, 2022). "For example, PIM2-mediated activation of HSF1 induces transcriptional upregulation of PD-L1 to suppress the immune system, enabling cancer cells to evade immune surveillance." (PMID 35180892, 2022). "For example, HSF1 is often overexpressed in cancer cells where it supports a malignant phenotype whereas HSF1 hypoactivation in neurodegenerative disorders results in the formation of toxic aggregates." (PMID 36010586, 2022). "We describe the short history in which HSF1 has been recognized to have strong and positive involvement in cancer before discussing novel discoveries in HSF2 and cancer relationship." (PMID 36430241, 2022).
cancer (continued). "HSF1 maintains ribosomal biogenesis and promotes glycolysis, which is the main energy-producing metabolic pathway from glucose in cancer cells." (PMID 35311075, 2022). "Due to the connection between hypoxia and cancer, it has also been demonstrated that HSF1 and HIF1A are closely related to tumor formation." (PMID 36347941, 2022). "Compared to HSF2, it is now widely known that HSF1 and its target HSPs are positively related to cancer (tumor) development and progression." (PMID 36430241, 2022). "HSF1 is highly expressed in a variety of tumors and high HSF1 expression in tumor tissues is negatively correlated with the prognosis of cancer patients." (PMID 36036010, 2022). "Recently, Mendillo and his colleagues reported that HSF2 physically and functionally interacts with HSF1 across diverse types of cancer." (PMID 36430241, 2022). "Recent genome-wide studies revealed that HSF1 reprograms the transcription of genes involved in a multitude of processes, including metabolism, gametogenesis, aging, and cancer." (PMID 36245043, 2022). "Nevertheless, HSF1 appears to play a dominant role in this network, perhaps also through activation in the cancer cells themselves, as reflected by our mass-spectrometry analysis of proteins secreted from KPC-shBrca2 cells." (PMID 36316305, 2022). "The relationship between HSF1 and mTOR, also seen in other cancer types, was demonstrated as a necessary component for MYC-driven HCC." (PMID 35311075, 2022). "Flavaglines were also shown to bind to prohibitins (PHB) responsible for regulation of important signaling pathways, and to inhibit the transcriptional factor HSF1 deeply involved in metabolic programming, survival, and proliferation of cancer cells." (PMID 34104125, 2022). "The aim of this study was to investigate the efficacy of combinational anticancer therapy using an HSF1 inhibitor found earlier in our laboratory and the autophagy inhibitor, CQ, in colon carcinoma cells taken from cancer patients." (PMID 35893747, 2022). "At the top of this list there is “HSF1 activation”, whose importance in several cancer types has been demonstrated." (PMID 36329531, 2022). "The transcription factor HSF1 drives tumor development by regulating the expression of heat shock proteins, inhibiting apoptosis, promoting cancer cell proliferation and metastasis, and facilitating DNA repair." (PMID 36036010, 2022). "The main HSP regulator, HSF1, is overactivated in cancer cells and autophagy sustains the survival of malignant cells." (PMID 35893747, 2022). "While in READ, HSF1 expression was negatively correlated with CD4 + T cell and positively correlated with cancer associated fibroblast (CAF), CD8 + T cell and NK cell." (PMID 35006040, 2022). "In this model of RAS-driven carcinogenesis, the overall incidence of tumors was much lower when Hsf1 was deactivated, yet once a neoplasm was formed, the proportion of benign and malignant tumors was unchanged." (PMID 35311075, 2022). "The transcriptional factor HSF1 (heat shock factor 1) is deeply involved in metabolic programming, survival, and proliferation of cancer cells in addition to heat-shock response." (PMID 34104125, 2022). "In cancer cells, one mechanism underlying HSP60 overexpression is the mediation of its transcriptional regulation by the proto-oncogenes c-MYC and HSF1." (PMID 35180892, 2022). "HSF1 itself has long been reported to play critical roles in cancer progression, metastasis, and drug resistance." (PMID 35326716, 2022). "Among members of the HSF family, HSF1 is reported to be the major regulator of increased HSPs in cancer, and switches on during the development of cancer." (PMID 36069792, 2022). "In cancer cells, the protective function of HSPs and their main regulator, HSF1, contributes to the survival of tumor cells and their metastatic spread." (PMID 35893747, 2022).
cancer (continued). "HSF1 appears to promote cancer by regulating genes distinct from its heat stress‐induced gene targets but has multiple functions to support tumour growth and progression." (PMID 35080342, 2022). "Heat Shock Factor 1 (HSF1), a transcription factor frequently overexpressed in cancer, is activated by proteotoxic agents and participates in the regulation of cellular stress response." (PMID 36010586, 2022). "Unsurprisingly, the cytoprotective properties of HSF1 are exploited by cancers to promote cell survival, proliferation, invasion and metastasis." (PMID 35311075, 2022). "Because of the dependence of cancer cells on HSF1, HSF1 can be used as an effective prognostic biomarker and is an attractive therapeutic target." (PMID 35180892, 2022). "HSF1 has long been reported to play crucial roles in cancer progression, metastasis, and drug resistance." (PMID 35326716, 2022). "A high level of HSF1 expression predicts disease progression and a shortened survival time in patients with different types of cancer." (PMID 35180892, 2022). "On the other hand, HSF1 plays an important role as a transcription factor in regulating a process called metabolic reprogramming in cancer cells." (PMID 35990198, 2022). "Further, the generated cell line cannot only be used to look for novel HSF1 activators, but also for HSF1 repressors as potential therapeutics for various cancer types." (PMID 35218516, 2022). "They found that HSF2 physically and functionally interacts with HSF1 across diverse types of cancer." (PMID 36430241, 2022). "Overall, our findings suggest that BRCA-mut cancer cells promote a stressful TME that leads to the activation of HSF1 in a subset of PSCs." (PMID 36316305, 2022). "The cancer genome atlas (TCGA) data showed a significant positive correlation between the expression of HSF1 and LINC00857." (PMID 36010849, 2022). "HSF1 is a transcription factor that promotes tumorigenesis by regulating cancer-specific transcription." (PMID 36339263, 2022). "Our pan-cancer analysis found that amplifications in HSF1 and MYC genes (both situated at this locus) co-occurred in a high percentage of cases." (PMID 35311075, 2022). "The expression, activity, and nuclear localization of HSF1 are generally elevated in cancers in response to the increased biosynthetic demands and oncogenic stresses resulting from rapid cell proliferation and the mutant cancer proteome." (PMID 36245043, 2022). "In this work, we review the role of HSF1 and HSPs in protein quality control in physiological conditions and in cancer." (PMID 35311075, 2022). "Induction of proteotoxicity, the UPR and heat shock response pathways in AML cells by WFA is consistent with data from a previous study that used an HSF1-reporter screen to identify anti-cancer compounds capable of inducing the endogenous heat shock response." (PMID 35368048, 2022). "Previously reported HSF1 pathway inhibitors have been evaluated in cellular and mouse xenograft cancer models." (PMID 36245043, 2022). "HSF1 was significantly overexpressed in carcinoma than normal tissue by UALCAN and Oncomine database." (PMID 35006040, 2022). "Heterozygotes developed more carcinomas, while among Hsf1 wild-type mice, sarcomas were more common." (PMID 35311075, 2022). "It was shown that HSP27 interacts with HIF-1α, while HIF-1α and HSF1 regulate HSP27 expression in cancer cells." (PMID 33806538, 2021). "Several studies indicate that HSF1 can drive migration and invasion facilitating the malignant transformation and progression of cancer; however, the detailed mechanisms of its pro-metastatic activity are not fully understood." (PMID 34198675, 2021). "The present study showed that DNA methylation of HSF1 was downregulated in most common cancers, which is consistent with the upregulation of the HSF1 expression." (PMID 34239690, 2021). "In cancer cells the constitutively (phospho-) activated master transcription factor HSF1 orchestrates the major proteotoxic defense." (PMID 34188043, 2021).